VIPR2 (vasoactive intestinal peptide receptor 2)
Diseases named in the same sentence as VIPR2 in open-access papers (continued):
Sharing a sentence is not in itself a finding about the gene and the disease.
esophageal cancer (1 paper, 2021). A primary or metastatic malignant neoplasm involving the esophagus. "Survival univariate/multivariate COX analysis revealed that five genes, ZBTB16, AQP4, ADCYAP1R1, PDGFD, and VIPR2, and two microRNAs, miR-99a-5p, and miR-508-5p, were related to esophageal cancer prognosis." (PMID 34329340, 2021).
Hepatic steatosis (1 paper, 2024). Steatosis is a term used to denote lipid accumulation within hepatocytes. "Specifically, both global inhibition of VIP-producing neurons and the targeted removal of the neuroinhibitory control of ILC3 (namely VIPR2) reduced hepatic steatosis in a preclinical model of MASLD induced by an HFD." (PMID 39761015, 2024). "Using both conditional genetic inactivation of VIPR2 in ILC3 and chemogenetic-mediated inhibition of VIP-producing neurons, we found that hepatic steatosis can be attenuated by modulation of VIPergic signaling in innate lymphoid cells." (PMID 39761015, 2024).
mood disorder (1 paper, 2019). A cognitive disorder a disturbance in which the person's mood is hypothesized to be the main underlying feature. "It is in high LD with a second VIPR2 3ꞌ UTR SNP, rs885861, that was associated with mood disorders in Spanish subjects." (PMID 31689297, 2019).
opioid dependence (1 paper, 2022). "A SNP in the 3′ untranslated region (3’ UTR) of the circadian Vasoactive Intestinal Peptide Receptor 2 (VIPR2) gene (VIPR2 SNP rs885863) is significantly noted in a pool of patients suffering from opioid dependence." (PMID 36233105, 2022).
refractive error (1 paper, 2019). A defect in the focusing of light on the retina as in astigmatism, myopia, or hyperopia. "The recent mega-study of refractive errors reported 2 lead SNPs in the VIPR2 region: rs60884546 located within a VIPR2 intron, and rs7789096 located ~140 kb upstream of VIPR2 transcription start site." (PMID 31796800, 2019).
tauopathy (1 paper, 2019). Neurodegenerative disorders involving deposition of abnormal tau protein isoforms (tau proteins) in neurons and glial cells in the brain. "Because we did not generate an alternative targeted insertion of a tTA transgene for our current work, we cannot determine if the loss of the genes disrupted by the Vipr2-Ptprn2 tTA-TgINDEL directly affect the tauopathy phenocopy of rTg4510." (PMID 31171783, 2019). "Precisely defining the effects of the Vipr2-Ptprn2 tTA-TgINDEL allele on the tauopathy phenocopy of rTg4510 is complex and in some ways problematic." (PMID 31171783, 2019).
tumor (11 papers, 2013 to 2025). "We have also shown that vasoactive intestinal peptide–VIPR2 signaling affects the polarity and activation of tumor-associated macrophages, which is another strategy for cancer immunotherapy apart from the activation of effector T cells." (PMID 37405999, 2023). "VIPR2-selective blockade is also expected to have additive/synergistic anti-tumor effects in combination with anti-cancer drugs." (PMID 37405999, 2023). "As previously reported, blockade of VIPR2 signaling suppresses tumor growth by enhancing the polarization and phagocytic function of M1-type macrophages in CT26 tumor-bearing mice." (PMID 37405999, 2023). "In contrast, stable expression of exogenous VIPR2 promoted VIP-induced tumor cell migration, an effect that was inhibited by the addition of a PI3-kinase (PI3K)γ inhibitor or a VIPR2-selective antagonist." (PMID 36237322, 2022). "GRIA4 showed hypermethylation in 6/10 tumour samples, while VIPR2 was hypermethylated in 7/10 tumour samples." (PMID 32599859, 2020). "This analysis confirmed the significant lower expression level of GRIA4 and VIPR2 in tumour tissues than in normal ones." (PMID 32599859, 2020). "Our results demonstrated protein and transcript expression of VIPR2 in normal and tumour tissue enriching the knowledge of its possible involvement in CRC." (PMID 32599859, 2020). "In this study, we demonstrated for the first time that KS-133, a VIPR2-selective antagonistic peptide, increases M1-type macrophage markers and decreases M2-type macrophage markers in vitro, exhibits anti-tumor efficacy in vivo, and enhances the pharmacological efficacy of an anti-PD-1 antibody." (PMID 37405999, 2023). "It has been reported that daily subcutaneous administration of VIPhyb, an antagonist of both VIPR1 and VIPR2, induces anti-tumor effects against CT26 cells implanted to severe combined immunodeficient (SCID) mice and enhances the pharmacological effects of an anti-PD-1 antibody." (PMID 37405999, 2023). "In this study, we aimed to examine whether the selective blockade of VIPR2 by KS-133 changes the polarization of macrophages and induces anti-tumor effects." (PMID 37405999, 2023). "The absence of hypermethylation of GRIA4 and VIPR2 associated CGIs in CRC tissue samples with low content of tumour cells highlights the high specificity of these two biomarkers for CRC detection." (PMID 32599859, 2020). "Thus, we expected that the selective blockade of VIPR2 by KS-133, both alone and in combination with immune checkpoint inhibitors, such as anti-PD-1 antibodies would promote cancer-immune activation and induce anti-tumor effects." (PMID 37405999, 2023). "In summary, our work was focused on the methylation and expression analyses of GRIA4, VIPR2, SPOCK1 and SLC6A3, belonging to gene families involved in the crosstalk between tumour cells and the environment." (PMID 32599859, 2020). "In addition, VIP is released from tumor and immune cells, and it regulates immune reactions such as anti-inflammatory activities through interactions with VIPR1 and VIPR2." (PMID 37405999, 2023). "However, we did not detect a statistically significant reduction of VIPR2 at protein level in tumour tissues, probably for the large variability among the samples, although a tendency towards downregulation can be observed." (PMID 32599859, 2020).
cancer (7 papers, 2017 to 2025). A tumor composed of atypical neoplastic, often pleomorphic cells that invade other tissues. "Several lines of evidence support associations of VIPR2 with cancer and immunity." (PMID 37405999, 2023). "Deregulation of VIPR2 signaling may be a potential mechanism underlying the development of cancer cell pathology." (PMID 36237322, 2022). "Another interesting result was the relationship between the stability and anti-cancer activity of NPs containing a VIPR2 antagonist." (PMID 37405999, 2023). "Our data have revealed that specific blockade of VIPR2 by KS-133 has therapeutic potential for cancer both alone and in combination with immune checkpoint inhibitors." (PMID 37405999, 2023). "VIPR2 was selected for its functional role and the involvement of vasoactive intestinal peptide receptors in cancer, while GRIA4 was chosen because it has previously shown methylation alterations in CRC tissues as well in plasma and stool samples." (PMID 32599859, 2020). "To investigate whether VIPR2 expression affects cancer cell motility, we examined the cell migration of MDA-MB-231 cells." (PMID 36237322, 2022). "Our findings conclusively demonstrated that VIPR2 regulates cancer cell migration." (PMID 36237322, 2022). "We next established several cancer cell lines stably expressing exogenous VIPR2." (PMID 36237322, 2022). "However, the pathophysiological roles of VIPR2 in cancer remain largely unknown." (PMID 36237322, 2022). "For instance, NOVA1, NRXN1, TMEM132C, USP44, VIPR2, and ZSCAN23 were consistently downregulated in nine cancers." (PMID 28060724, 2017). "Furthermore, VIPR2 has been shown to form homodimers and oligomers, which are involved in VIP-induced cancer cell migration." (PMID 39869563, 2025). "The elucidation of the roles of VIPR2 in PI3K activity revealed in this study and the increased VIPR2 gene expression in some cancers suggest the possibility that VIPR2 may play a part in cancer development." (PMID 36237322, 2022). "However, a role for VIPR2 signaling in cancer cell migration has not been completely elucidated." (PMID 36237322, 2022).
infection (5 papers, 2021 to 2024). The state of being infected such as from the introduction of a foreign agent such as serum, vaccine, antigenic substance or organism. "Like the significantly overexpressed gene HSP90, which is a receptor for Dengue virus and Japanese encephalitis virus, many other receptor genes, such as Ptprf and Vipr2, were significantly highly expressed in grouper after RGNNV infection." (PMID 34185811, 2021).
psychiatric disorder (3 papers, 2020 to 2022). A disorder characterized by behavioral and/or psychological abnormalities, often accompanied by physical symptoms. "Next, we investigated the pharmacological efficacy of KS-133 in a mouse model of psychiatric disorders on the basis of early postnatal activation of VIPR2." (PMID 34819858, 2021). "Lymphocytes from patients with these mutations exhibited higher VIPR2 gene expression and VIP-induced cAMP responsiveness, but mechanisms by which overactive VPAC2 signaling may lead to these psychiatric disorders are unknown." (PMID 32581681, 2020). "Although the mechanisms by which overactive VIPR2 signaling may lead to psychiatric disorders are still not fully understood, activation of the cAMP/PKA pathway downstream of VIPR2 might be at least partly involved in neuronal development impairment and behavioral abnormalities." (PMID 34819858, 2021).
VIPR2 also shares sentences with these, for which no sentence is quoted: migraine (6 papers); Arthritis (4); glioblastoma (4); autoimmune disease (3); Cognitive impairment (3); experimental autoimmune encephalomyelitis (3); glioma (3); Hyperglycemia (3); rheumatoid arthritis (3); adenocarcinoma (2); allergic asthma (2); autism spectrum disorder (2); cervical carcinoma (2); colon cancer (2); colorectal cancer (2); depression (2); Headache (2); leiomyoma (2); melanoma (2); multiple sclerosis (2); Obesity (2); osteosarcoma (2); Parkinson (2); type 2 diabetes (2); allergic rhinitis (1); Allergy (1); atherosclerosis (1); bacterial infection (1); bipolar disorder (1); bladder cancer (1).
A further 32 diseases each share a sentence with VIPR2 in 1 paper.